RN7SL62P (RNA, 7SL, cytoplasmic 62, pseudogene)
Gene: Miscellaneous RNA gene on chromosome 1 (52,714,399 to 52,714,695, forward strand). Ensembl gene ENSG00000239640.
Homologues: Orthologues: chimpanzee Metazoa_SRP (99% identical), macaque Metazoa_SRP (93% identical). Paralogues in human: RN7SL1 (81% identical), RN7SL2 (81% identical), RN7SL45P (80% identical), RN7SL126P (79% identical), RN7SL3 (79% identical), RN7SL679P (79% identical), RN7SL186P (78% identical), RN7SL660P (78% identical), RN7SL386P (78% identical), Metazoa_SRP (77% identical), RN7SL296P (77% identical), RN7SL326P (77% identical), and 703 more.